RN7SKP73 (RN7SK pseudogene 73)
Gene: Miscellaneous RNA gene on chromosome 5 (5,126,046 to 5,126,337, forward strand). Ensembl gene ENSG00000223007.
Homologues: Orthologues: chimpanzee 7SK (97% identical). Paralogues in human: RN7SKP176 (75% identical), RN7SKP243 (71% identical), RN7SKP48 (71% identical), 7SK (71% identical), RN7SKP162 (71% identical), RN7SKP193 (70% identical), RN7SKP199 (70% identical), RN7SKP203 (70% identical), RN7SKP204 (70% identical), RN7SKP79 (70% identical), RN7SKP25 (70% identical), RN7SKP71 (70% identical), and 284 more.